TNF (tumor necrosis factor)
Diseases named in the same sentence as TNF in open-access papers (continued):
Sharing a sentence is not in itself a finding about the gene and the disease.
cancer (continued). "Various inflammatory biomarkers have been discussed in cancer studies as they have been linked to advanced cancer stages, resistance to immunotherapy, and poor prognosis: tumor necrosis factorα (TNF-α), interferon-γ (IFN-γ), and interleukin (IL)-1, IL-6, IL-8, IL-10, IL-11, and IL-17." (PMID 36499628, 2022). "In addition, it is well established that exposure to EGCG inhibits the action of tumor necrosis factor (TNF-α), which in turn causes cancer cells to undergo the process of apoptosis." (PMID 36142616, 2022). "Additionally, SSD has shown a strong ability to stop the TNF-α-accelerated loss of mitochondrial membrane potential to cause apoptosis in HeLa cells while inducing cancer cell invasion and angiogenesis in HUVECs." (PMID 36547471, 2022). "In regard to the factors affecting cancer risk other than TNF inhibitors, increasing age, male sex, presence of chronic liver disease, and high PDC by nbDMARDs, corticosteroids, and NSAIDs were positively associated with cancer occurrence in multivariable analysis based on cohort before matching." (PMID 35945635, 2022). "Increased expression of proinflammatory cytokines, such as IL6 and TNF, in the stress-associated cancer cell population suggests that these cells could have a substantial contribution to paracrine signaling." (PMID 35196078, 2022). "Our results underline that IL-6 and TNFα SNPs could be potential markers of baseline pain intensity and opioid dose requirements in pediatric cancer patients." (PMID 35335997, 2022). "Additionally, the Western dietary pattern has been correlated with pro-inflammatory markers associated with cancer-related fatigue, including tumor necrosis factor (TNF)-α, C-reactive protein, interleukin (IL)-6, and IL-8." (PMID 35454890, 2022). "This review will present an updated summary that explores the potential role of TNF in cancer and the various underlying mechanisms that could explain an interference." (PMID 36358688, 2022). "Increased TNF-α secretion caused by Fusobacterium nucleatum infection modulates the expression levels of the cancer-carcinogenic target MiR-21, which in turn modulates the secretion of additional inflammatory cytokines, including TNF-α, IL-6, IL-17A, and IL-21." (PMID 36140470, 2022). "Therefore, cancer risk and other serious side effects should be monitored when using TNF-α or its inhibitors for treatment." (PMID 36358977, 2022). "Similarly, TNF-α, IL-6 and IL-1β mediate cancer-associated inflammation, and promote tumorigenesis through generation of a profitable environment by enhancing recruitment of immune-suppressor cells." (PMID 36417428, 2022). "Red and processed meat in the diet with a lower LLDS have higher saturated fatty acids, saturated fatty acids can increase some pro-inflammatory substances such as TNF-α in the body that causes inflammation and tissue damage, and the body's cells are prone to various cancers, including BrCa." (PMID 35685489, 2022). "Thus, the tight interaction of the inflammatory pathways with the cellular pathways linked to cancer biology features the role of TGFβ signaling modulations in promoting an aggressive CAC phenotype in Winnie-ApcMin/+-TNF-KO mice." (PMID 36499472, 2022). "TNFα was found to be expressed in tumors from early stages of disease and on, and its continuous presence contributed to chronic inflammation, considered the Seventh Hallmark of Cancer." (PMID 35663982, 2022). "Lastly, the ongoing issues surrounding cancer risk and TNF inhibitors may have shaped the behavior of physicians." (PMID 35945635, 2022).
cancer (continued). "In addition, all pathways identified as enriched by the KEGG analysis were associated with TNF signaling pathway, transcriptional misregulation in cancer and pathways in cancer." (PMID 35303006, 2022). "Firstly, TNF-α caused inflammation in cancers was commonly implemented in numerous investigations." (PMID 35681644, 2022). "TNF-α is one of the key chemical mediators implicated in inflammation-associated cancers." (PMID 35980113, 2022). "Notably, accumulation of inflammatory mediators, such as transcription factors NFκB and STAT3 as well as cytokines IL-6 and TNF-α, has been linked to local and systemic immunosuppression associated with the progression of cancer." (PMID 35163219, 2022). "For example, physicians might have avoided prescribing TNF inhibitors to patients clinically judged to be at high risk for cancer, thereby affecting the risk of cancer in TNF inhibitor users." (PMID 35945635, 2022). "Evidence has also shown that TNF-α is the key link that causes cancer pain in cancer patients." (PMID 35719369, 2022). "Consequently, TNF-α shifts cancer cells from the dormant phase, G0/G1, to the more susceptible proliferative phase." (PMID 36234520, 2022). "Thus, we demonstrate that depletion of immunosuppressive TAMs and MDSCs results in decreased TNF-α, causing increased IL-33 levels in carcinoma cells that result in increased cytotoxic T cell response to combat metastatic PDA." (PMID 36256464, 2022). "Furthermore, the KEGG pathway analysis also found that some downregulated genes were significantly enriched in well-known cancer-associated pathways, including cell adhesion molecules, TNF, PPAR, and chemokine signaling pathways." (PMID 33627711, 2021). "However numerous studies suggest that anti-TNF-α treatments increase the risk for cancer, disqualifying this approach for PDAC." (PMID 34172716, 2021). "Some cancer cells are especially susceptible to TNF-α’s cytotoxic impact." (PMID 34711017, 2021). "When these cancer cells were transfected with a siRNA specific to GPx1, the resulting depletion of GPx1 caused markedly augmented TNF-α-induced apoptosis of all the cancer cells selected, which were then completely blocked by treatment with a pan-caspase inhibitor (zVAD-fmk)." (PMID 34158609, 2021). "At the same time, continuous use of systemic anti-TNF/anti-LTα biologics, such as Etanercept, could result in increased risk of cancer development." (PMID 33917839, 2021). "Based on this result, it was investigated whether farrerol could improve lipid wasting caused by TNF-α, a typical factor of Cachexia, in various cancer types." (PMID 34502316, 2021). "In conclusion, with recent data suggesting a relatively low risk of increased risk of developing cancer due to anti-TNF therapy, patients and care providers should feel assured when prescribing these medicines however stay vigilant of any future investigations into this topic." (PMID 34648530, 2021). "On the other hand, high levels of TNF-α are associated with cancer progression and metastasis." (PMID 34379689, 2021). "Polymorphisms in the TNFα gene have also been studied related to cancer incidence." (PMID 33540543, 2021). "Moreover, the effect of TNF on cancer invasiveness is tightly linked to the regulation of the miRNA expression." (PMID 33917839, 2021). "Considering that the TNFα and TGFβ signaling strength in cancer cells reflects the TNFα and TGFβ levels in intercellular matrix, we ask whether intracellular TNFα and TGFβ signaling is associated with infiltration of any specific type of immune cells in BLBC." (PMID 33767579, 2021). "TNF-α can promote most of the abnormalities found during cancer cachexia: loss of weight, loss of appetite, increased thermogenesis, alterations in carbohydrate, protein and lipid metabolism, insulin resistance, and wasting of muscle by the activation of the breakdown of protein." (PMID 34371835, 2021).
cancer (continued). "TNF-α expression was observed to upregulate expression of several cancer-associated genes in the epithelial cells which include extracellular matrix (ECM) remodeling genes such as MMP9, PLAU, FN1 and ICAM1, chemokines such as CCL2, CXCL2, CXCL3 and CXCL10 and regulatory genes such as UBD and PTGS2." (PMID 34946170, 2021). "In contrast to insulin resistance, cancer cachexia may be driven by inflammation as and IL-6, IL-1, and TNF-α per se can cause muscle catabolism." (PMID 33801684, 2021). "Since TNF, also known as cachectin, is strongly implicated as a mediator of CNS inflammation during cachexia, it is plausible that this described brain–fat axis mediates some of the adipose tissue remodeling and wasting observed during cancer cachexia." (PMID 34439145, 2021). "Importantly, NF cells also expressed considerably higher levels of effector molecules (IFN-γ and TNF-α) and exhibited increased degranulation (induction of CD107a expression) associated with enhanced cytotoxicity against various cancer cell lines in vitro." (PMID 32939032, 2021). "Inflammation is one of the hallmarks of cancer and it was found that CC variant of rs2853669 was linked to increased level of inflammatory cytokines IL-6 and TNF-α, which may contribute to cancer malignancy." (PMID 34440361, 2021). "According to the present allele frequency distribution data of all cancer patients, only 27 patients of 203 (13%) had the TNF-α 308G/A (rs1800629) mutation, whereas approximately seven times more patients carried the wild-type allele (176 patients, i.e., 87% of the total number)." (PMID 34900737, 2021). "In summary, neutrophil secretion of and reaction to TNF-α causes many interactions in the TME may be exploited as potential targets in cancer therapy." (PMID 33986746, 2021). "The results showed that the top 10 Kyoto Encyclopedia of Genes and Genomes (KEGG) pathways for TIMPs and their 20 correlated genes were mainly associated with proteoglycans in cancer, the IL-17 signalling pathway, the TNF signalling pathway, the GnRH signalling pathway, and others." (PMID 34781885, 2021). "Moreover, TNFα associated with chronic inflammation can be held responsible for the observed phenomenon of cancer cell specific resistance to TNFα-induced cell death." (PMID 34445397, 2021). "TNFα-238G>A polymorphism has been reported to alter the risk of several types of cancers, such as HCC, breast cancer, lung cancer, non-Hodgkin lymphomas, and prostate cancer.Interleukin-18 (IL-18) belongs to the IL-1 cytokine superfamily and it is a novel proinflammatory cytokine." (PMID 33773554, 2021). "For KEGG pathway enrichment analysis, we found that these candidate DE-mRNAs were significantly enriched in several cancer-associated pathways, such as cell cycle, pathway in cancer, TNF signaling pathway, Jak-STAT signaling pathway, and NF-kappa B signaling pathway." (PMID 32500028, 2020). "TNF-α is a cytokine, which exerts a dual role in immunomodulation (inflammation, immune surveillance, and hematopoiesis) and tumorigenesis, while the transcription factor, NFκβ, regulates proinflammatory cytokines (TNF-α and IL-1), and it has a pathogenic function in cancer and inflammation." (PMID 32765628, 2020). "Inflammatory cytokines such as TNF-α can induce Mint3 expression in cancer-associated fibroblasts." (PMID 32826949, 2020). "In fact, leptin signaling is linked to the development of several cancer types, including pancreatic cancer, through different mechanisms including the production of inflammatory factors (IL-1, IL-6, and TNF-α), which have been shown to promote tumor invasion and metastasis." (PMID 32604970, 2020). "It has been reported that cancer associated adipocytes secrete IL-6 and TNF-α." (PMID 32796516, 2020). "Along with previous observational studies, the present study strengthened the evidence that TNF inhibitors might reduce the risk of common cardiovascular events but increase risk of overall and certain cancers." (PMID 32805626, 2020).
cancer (continued). "Cancer pain is closely associated with IKKβ/NF-κB, IL-1β, IL-6, and TNF-α." (PMID 32431607, 2020). "Finally, TNF has emerged as an important risk factor for cancer progression, invasion, and metastases and is a key intermediary of chronic inflammation associated with cancer." (PMID 33585180, 2020). "In addition to the risk factors of the general population, advanced cancer stages, increased TNF-α, and decreased clusters of differentiation 4 (CD4) T cells and albumin globulin ratios were risk factors for the disease in cancer patients." (PMID 33232275, 2020). "TNF-α is one of the inflammatory mediators associated with the development of carcinogenesis, and it plays a key role in the mechanisms of the loss of skeletal muscle, systemic inflammation, and the loss of adipose tissue in cancer cachexia." (PMID 32020864, 2020). "Furthermore, a high level of TNF-α is associated with aggressive behaviour and poor prognosis in many malignant cancers." (PMID 32592356, 2020). "Therefore, the TNFα-induced upregulation of CASP9 via NF-κB-mediated FFL should be a molecular mechanism underlying the TNFα-promoted apoptosis of cancer cells induced by DOX." (PMID 32225068, 2020). "Here, we aimed to evaluate the CVDs and cancers that are causally associated with TNF levels and which could be targeted with TNF-modifying therapies." (PMID 32805626, 2020). "TNFα has been associated with cancer cell motility, invasion and EMT." (PMID 32391269, 2020). "Treatment of BEAS-2B cells for one day resulted in over-representation of Citrate cycle and Mismatch repair pathways when compared with the controls, while the longer, five-day exposure was associated with enrichment of TNF signaling pathway and Pathways of cancer." (PMID 33374749, 2020). "For example, evidence from our studies indicated that co-culturing of TNBC cells with mesenchymal stromal cells (MSCs) or cancer-associated fibroblasts (CAFs) in the presence of TNFα or IL-1β stimulation has given rise to contact-dependent increase in CXCL8, CCL2 and CCL5 levels in the co-cultures." (PMID 32605277, 2020). "The study aims at identifying polymorphisms in the IL-1, tumor necrosis factor-alpha (TNF-α) and IL-10 coding genes to clarify the association between those changes and cancer risks to early locate those individuals at higher risks for gastrointestinal malignancies development." (PMID 32751137, 2020). "Conversely, TNF-α is implicated in various biological processes, such as inflammation, cell survival, cell proliferation, and cell differentiation, which implies that this molecule is a double-edged sword in cancer treatment." (PMID 32455774, 2020). "Anorexia in cancer patients is associated with the predominance of signals suppressing appetite in the hypothalamus—proopiomelanocortin and anorexigenic action of pro-inflammatory cytokines: IL-1α, IL-1β, IL-6, TNF-α." (PMID 33158194, 2020). "Furthermore, the expression of IL-4, IL-7, IL-10, IFN-α, and TNF-α in the same cancer model was, in all cases, associated with neutrophil as well as CD8+ T cell-mediated rejection." (PMID 33105656, 2020). "Additionally, patients with GC are often malnourished, and poor oral nutritional intake and protein loss caused by primary lesions cause cancer cell to secrete cytokines, such as tumor necrosis factor-alpha, that adversely affect catabolic metabolism." (PMID 32758144, 2020). "In addition, elevated serum levels of TNFα were associated with cancer stage and progression, and was linked to poor prognosis." (PMID 32317968, 2020). "We conducted a Mendelian randomization study to explore whether TNF levels are causally related to cardiovascular disease and cancer." (PMID 32805626, 2020).
cancer (continued). "Inflammation has been shown to be a key factor in promoting tumorigenesis primarily through the NF-κB pathway, which is activated in response to proinflammatory cytokines such as TNF the increased levels of which are strongly associated with the aggressive phenotype of various cancers." (PMID 31001473, 2019). "NO and TNF-α are both inflammatory mediators associated with cancer metastasis." (PMID 30787353, 2019). "Besides IL-1, IL-6, and IL-8, other proinflammatory factors are also associated with the occurrence and development of cancer, such as TNF-α, TGF-β, BCA-1, and so on." (PMID 31832112, 2019). "By contrast, TNF-α −308G allele was regarded as a risk factor in some diseases and cancers." (PMID 31652851, 2019). "TNF-α, located on chromosome 6 (6 p21.33), is a pro-inflammatory, pleiotropic cytokine which has been implicated in the pathogenesis and progression of various cancers." (PMID 31244280, 2019). "Moreover, preclinical studies found that blocking TNFR2 is sufficient to reduce the development of TNF-activated cells as well as to increase TNF-associated cancer cell death." (PMID 31239840, 2019). "Although TNF-α is usually secreted from activated macrophages, it is unclear whether immune cells in adipose or skeletal muscle tissues are associated with increases in the production of TNF-α in cancer cachexia." (PMID 30754663, 2019). "A research in Korea revealed that TNF-α −238A allele may play a protective role against various types of cancer." (PMID 31652851, 2019). "Since TNFα can induce GM-CSF expression and secretion in several cancer cells, our results may furthermore suggest that a similar pattern of mechanisms may underlie TNFα induced production of GM-CSF by various cancer cells and tissues." (PMID 31581558, 2019). "Alternating the consumption of β‐glucan and quercetin significantly decreased the TNF‐α level, increased the relative abundance of Parabacteroides, and downregulated three genes (Hmgcs2, Fabp2, and Gpt) that are associated with inflammation and cancer." (PMID 31660141, 2019). "Cancer patients often suffer from the condition, cachexia, in which there is a progressive loss of fat and muscle mass leading to overwhelming weakness; it is attributed to the action of cytokines such as TNF-α and IFN-γ, which are released by macrophages." (PMID 30755785, 2019). "Moreover, other studies, although they consider only BC patients treated with CHT, associate high levels of serum TNF-α with a reduced risk of cancer progression." (PMID 30658426, 2019). "Several molecular mechanisms could be implicated in the cancer-related decrease in the activities of antioxidant enzymes such as a downregulation of synthesis by proinflammatory cytokines such as TNFα and IL-1." (PMID 31191796, 2019). "Here, we demonstrate that DAPT, inhibitor of γ-secretase that participates in activation of Notch receptors, inhibited the migration and invasion of TNBC cells that were grown in “Contact” co-cultures with MSCs or with patient-derived cancer-associated fibroblasts (CAFs), in the presence of TNFα." (PMID 31105691, 2019). "Approximately 28% of cancers are susceptible to direct cell killing mediated by soluble TNF." (PMID 30170620, 2018). "Both TGF-β and TNF-α have been associated with increased cancer cell proliferation and motility." (PMID 30558665, 2018). "However, a total inhibition of inflammation can also worsen cancer prognosis, as noted from the use of TNFα blockers resulting in an increased risk of lymphoma development." (PMID 30384444, 2018). "However, owing to limitations in the sample size, future studies are required to assess the association between genotypes including TNF-α-308G>A polymorphism and clinical cancer prognosis." (PMID 30407345, 2018). "These previous reports highlight that TNF-α gene polymorphisms, especially -238A allele might act as a risk factor for cancer development and progression, which was consistent with our conclusions." (PMID 30413607, 2018).